ENSG00000201502
Synonyms: LOC124900325
Gene: Small nucleolar RNA gene on chromosome 12 (93,266,017 to 93,266,096, forward strand). Ensembl gene ENSG00000201502.
Gene Ontology:
Biological process: RNA processing
Cellular component: nucleolus
Homologues: Orthologues: mouse Gm26224 (69% identical), rat LOC120096384 (64% identical), zebrafish snord74 (62% identical). Paralogues in human: SNORD74B (66% identical).